TNF (tumor necrosis factor)
Diseases named in the same sentence as TNF in open-access papers (continued):
Sharing a sentence is not in itself a finding about the gene and the disease.
tumor (continued). "Upregulation of CD95 in tumor cells is activated by various stimuli including TNF-α, IFN-γ, interleukins, nitric oxide, chemotherapy and ionizing radiation." (PMID 28223543, 2017). "The entry of metastatic tumor cells into the liver has been shown to trigger a rapid release of pro-inflammatory cytokines including TNF-α." (PMID 28881729, 2017). "IL-6 and TNF-α were also more expressed within the Klrk1+/+ tumour demonstrating that NKG2D has a significant influence on the tumour microenvironment, boosting the production of key pro-inflammatory cytokines." (PMID 28128200, 2017). "Numerous studies have indicated that tumor cells exhibit constitutive production of TNF-α proinflammatory cytokines, IL-1α, IL-6, and GM-CSF (macrophage-granulocyte colony-stimulating factor)." (PMID 28785138, 2017). "After treatment period, cytokines, Interleukin 2, IL-6, IL-7, IL-10, IL-15, 1 L-17 and TNFα in CT-26 tumor bearing BALB/c mice serum were analysed." (PMID 29246138, 2017). "TNF-α produced by M1 macrophages promotes tumor cell proliferation and neoangiogenetic abilities through the induction of genes encoding anti-apoptotic molecules." (PMID 28804688, 2017). "This was achieved by fusing TNF-α with a peptide containing the CNGRC motif (NGR-TNF) sequence that interacts with CD13 on tumor vessels." (PMID 28665313, 2017). "DGLA has been shown to reduce the production/activity of tumor necrosis factor alpha (TNF α), while TNF α is implicated in both apoptosis and cell proliferation, thus having a paradoxical role in anti-cancer activity and tumor promotion." (PMID 29268695, 2017). "TNF-α can directly kill tumor cells by activating T lymphocytes and stimulating the human body toproduce cytokines and antibodies." (PMID 28388901, 2017). "Dynamic polyfunctionality analysis of adoptively transferred MART-1-specific TCR-engineered T cells showed that TNF-α+IFN-γ+ polyfunctional T cell delayed tumor relapse." (PMID 29157295, 2017). "Due to exhaustion of CD8+ T cells, tumor cells become very aggressive and secrete several pro-inflammatory cytokines, such as tumor necrosis factor alpha (TNF-α), interleukin-2 (IL-2), and interferon gamma (IFN-γ)." (PMID 28878676, 2017). "On turn, immature DCs are strongly hampered in their ability to produce TNF-α and other proinflammatory cytokines that inhibit tumor growth and metastasis." (PMID 28798777, 2017). "IL-17A and IL-23 cause the attraction of lamina propria myeloid cells (macrophages, granulocytes) to the tumor site which are the major source of IL-6 and TNF." (PMID 28881611, 2017). "Inflammatory cytokines made by host and/or tumor cells, such as TNF-α, IL-1, IL-6 and IFN-γ, have been reported to induce cancer cachexia in animal models." (PMID 28915700, 2017). "In the autocrine mode, tumor-derived TNFα can elicit anti-apoptotic signaling cascades as well as stimulating tumor growth, migration, and invasion." (PMID 28900035, 2017). "Tumor necrosis factor-α (TNF) was first described as a glycoprotein induced in response to endotoxin (the old name of which was cachectin) and has the capacity to kill tumor cells." (PMID 28358311, 2017). "TNF-α is a double edge sword in tumor development as it can promote cancer cell progression, or induce apoptosis depending on cellular interaction and the quantity of the cytokine." (PMID 28770521, 2017). "TNF-α expression within the tumor microenvironment promotes tumor cell invasion, migration and metastasis in several cancers." (PMID 28030810, 2017). "Lipopolysaccharide was then added as an immunostimulatory input before tumors were harvested and tumor secretions ultimately collected for TNFα measurements 18 hours later." (PMID 29018206, 2017). "An increase in intratumoral MCP-1, IFN-γ, and TNF-α expression was well correlated with more infiltration of CD8+ T cells into tumor tissues treated with oncolytic Ads." (PMID 28002796, 2017).
tumor (continued). "Compared to vehicle treatment, E7046 increased the myeloid cell-derived anti-tumor cytokine TNF-α, and reduced the levels of pro-tumor CXCL1, IL-10, and IL-6." (PMID 28920002, 2017). "In mice receiving Rik-overexpressing CD8+ T cells, TNF-α and granzyme B levels in tumor implants were less than those in mice receiving control CD8+ T cells." (PMID 28382040, 2017). "Ad.EPCR treatment elicited recruitment of macrophages and NK cells into the tumor microenvironment and increased IFNγ and TNFα levels in the pleural space." (PMID 27833109, 2016). "We sketch here how this can be done in the case of pure tumour evolutions, i.e. we ignore T-cells and TNF-α, for more details see (SI)." (PMID 27063839, 2016). "Increased levels of inflammatory cytokines, such as IL-6, IL-8, and TNF-α, are known to promote migration, invasion and metastasis of various types of cancer including breast cancer." (PMID 26888313, 2016). "Collectively, these data suggest that monocytes/macrophages in liver metastases induced tumor cell proliferation, migration and invasion, and upregulated S100a8 and S100a9 expression through TNFα-induced ERK activation." (PMID 27086923, 2016). "In our study, administration of anakinra significantly reduced expression of TNF alpha and IL-1B in bone and reduced levels of these molecules is likely to have contributed to the anti-tumour effects observed." (PMID 27765923, 2016). "Anakinra did not increase tumour cell apoptosis but reduced proliferation and angiogenesis in addition to exerting significant effects on the tumour environment reducing bone turnover markers, IL-1B and TNF alpha." (PMID 27765923, 2016). "We found that TNFα (1 μg/mouse) or IFNγ (5 μg/mouse) slightly increased tumor apoptosis while conjugation with TCP-1 peptide significantly inhibited tumor growth and increased tumor cell apoptosis." (PMID 27342639, 2016). "We have chosen MCA fibrosarcoma cell line, since a potent anti-tumor effect of TNF in vivo was originally discovered on methyl-cholantrene-induced tumors." (PMID 27148266, 2016). "The least level of production of either IL-6 or TNF-α was by spleen cells from mock-vaccinated tumor-bearing mice." (PMID 27598146, 2016). "Immune system promotes tumour vessel regeneration, migration, invasion, and metastasis by raising regulatory T lymphocytes and activation of related modulators such as IL-6 and TNF-α, C reactive protein, induction of neutrophilia, battering down immune system." (PMID 27732958, 2016). "In this model, a rapid increase of TNF-alpha, as well as other proinflammatory blood cytokines, was observed soon after intravenous administration of S. typhimurium into tumor-transplanted mice." (PMID 27190519, 2016). "As predicted, the ability of our compounds to compete with SMAC peptide for binding to the BIR3 domains of cIAP1 and cIAP2 correlated closely with ability to sensitize tumor cells to cytotoxicity induced by TNF and LT-α." (PMID 27617834, 2016). "We also examined the production of tumor-promoting cytokines, such as TNFα or interleukin-6, by 4T1-sup-activated PEC." (PMID 26834744, 2016). "In fact, AT is recognized now as potent endocrine organ by secreting pro-inflammatory cytokines (such as TNF-α and IL-6) and adipokines (such as leptin) in the tumor microenvironment." (PMID 27066006, 2016). "In general, the ability of these compounds to bind cIAP1 and cIAP2 in FP assays correlated well with their ability to sensitize tumor cells to TNF or LT-α induced cell death." (PMID 27617834, 2016). "IL-8 is highly expressed by tumor and stromal cells, and its expression in breast tumor cells is stimulated by TNF-α and/or IL-1β, two other important inflammatory cytokines in cancer development." (PMID 26970739, 2016). "Altered secretion profile of leptin, and adiponectin, and other inflammatory adipokines such as IL-6 and TNF-α, by interacting with signaling network, accelerate neoplasia." (PMID 27980732, 2016).
tumor (continued). "LSPS improved the immune response in H22 tumor-bearing mice by enhancing the spleen and thymus indexes, and increasing the levels of serum cytokines including tumor necrosis factor-α and interleukin-2." (PMID 27827862, 2016). "Chronic inflammation is one of the important factors of carcinogenesis, in which the inflammatory mediators such as TNFα, IL-1β and IL-6 secreted by macrophages promote tumour growth by deregulating the cell cycle checkpoints and cell repair machinery." (PMID 27270308, 2016). "The expression of t-PA is also regulated by a variety of effectors including cytokines tumor necrosis factor, interleukin, epidermal growth factor, and retinoid tumor promoters." (PMID 27635131, 2016). "Tumor-specific CD8+ T cell generation, associated with the secretion of Th1 cytokines (e.g., tumor necrosis factor α (TNFα) and interferon γ (IFNγ)), is desired in the context of anti-cancer therapy." (PMID 26993326, 2016). "In this regard, TNF and LT-α are commonly produced in the tumor microenvironment and a modified version of recombinant TNF that preferentially localizes to tumors is in Phase II/III clinical trials as a candidate cancer therapeutic." (PMID 27617834, 2016). "Taken together, our results suggested that deletion of IL6 promoted HCC development and increased tumor burden, NK cells, TNFα and IFNγ were significantly reduced in tumors of DDB1F/F, Alb-Cre+/−, IL6−/− mouse." (PMID 27556180, 2016). "Extensive research so far has revealed various roles of TNF-α such as in body development and immunity and in pathological responses such as inflammation, tumour growth, transplant rejection, rheumatoid arthritis, and septic shock." (PMID 26881177, 2016). "The central players involved in inflammation-mediated tumor progression include IL-1β, IL-6 and TNF-α." (PMID 26896068, 2016). "Classically activated macrophages, or M1 macrophages, activate the Th1 immune response and secrete high amounts of pro-inflammatory mediators, such as cytotoxic TNFα and nitric oxide (NO), to kill invading pathogens or tumor cells." (PMID 27020049, 2016). "On the other hand, the peripheral blood cell analysis disclosed that there were more CD3+ cells in the peripheral blood for the TNFα treated group, indicating that fewer T lymphocytes has entered the tumor for this group." (PMID 27342639, 2016). "IL-1β was also demonstrated to up-regulate the production of TNF-α by myeloid and/or tumor cells in the tumor microenvironment that significantly activates MDSC immunosuppressive functions." (PMID 27827871, 2016). "TNF-α is a multifunctional cytokine participating in immune disorders, inflammation, and tumor development with regulatory effects on energy metabolism." (PMID 27324794, 2016). "CXCL12 can also control tumor cell apoptosis, activating NF-κB, which represses radiation-induced tumor necrosis factor α (TNFα) production and tumor apoptosis." (PMID 26880981, 2016). "Meanwhile, they can release several cytokines, such as IFN-γ and TNF-α, to promote tumor control and improve prognosis of cancer patients." (PMID 27283904, 2016). "Although their mechanisms of activation differ, both CTLs and NK cells induce tumor cell death through death ligand cytokines of the tumor necrosis factor (TNF) ligand family." (PMID 27843441, 2016). "There was a positive association between survival and tumour islet density of mast cells (MCT and MCTC) expressing TNFα (p = 0.0004)." (PMID 27922077, 2016). "ZFSC reduced IFN-γ and TNF-α content in the serum of HT-1080 tumor-bearing mice and inhibit PD1 and PDL1." (PMID 27493673, 2016). "A significant inverse correlation was observed in the circulating TNF-α levels and TNF-α protein expression in the primary tumour tissues of PTC patients (r = −0.254, P = 0.021)." (PMID 26881177, 2016).
tumor (continued). "Members of the TNF family are associated with a wide range of immune processes and play an important role in cancer immune surveillance For example, TNF-α can mediate apoptosis selectively in tumor cells via death receptors involving TRAIL/FasL ligands." (PMID 28066412, 2016). "Notwithstanding, anti-TNF therapy has been demonstrated in orthotopic PDAC models to reduced primary tumor size and metastases." (PMID 27170998, 2016). "Recently the degradation of cIAP-1/−2 and the subsequent activation of NF-κB and induction of TNF-α was proposed as the main molecular effect of SM in tumor cells." (PMID 27655666, 2016). "A recent study demonstrated that expression of soluble TNF-α promoted tumor growth while membrane-bound TNF-α -expressing tumors had reduced growth and were mostly devoid of infiltrated myeloid cells." (PMID 27415000, 2016). "Treating cells from the 98Sc tumor with SM-164 and TNFα provoked DEVDase activity, which has been shown to predominantly reflect levels of active caspases-3, -7 and possibly -8." (PMID 27129149, 2016). "Depletion of TNF-alpha results in blood influx retardation and delayed bacterial tumor colonization." (PMID 27190519, 2016). "IL16, produced by CD8+T cells, can stimulate the secretion of tumor-related cytokines, such as TNF-α, IL1β, IL6, and IL1516." (PMID 27703190, 2016). "IL-1β, IL-18, IL-6, IL-8 and TNF-α are produced by macrophages through the activation of toll-like receptor signaling, and their production is involved in the clearance of tumor cells by macrophages." (PMID 27671753, 2016). "In the mouse model, SHH inhibitors significantly reduced tumor incidence and multiplicity, decreased the expression of IL-6, TNF-α, COX-2, STAT3, and NF-κB, and significantly induced apoptosis." (PMID 26716648, 2016). "Malignant cells from many different cancer types constitutively produce inflammatory cytokines and chemokines that are important in tumor growth and cancer progression, TNF and IL-6 being the most commonly reported." (PMID 26871292, 2016). "Previous in vivo and in vitro studies have shown that TNF-α functions during tumor initiation and development." (PMID 27658781, 2016). "We observed TNF-induced activation of caspase 8p18 primarily in infiltrating leukocytes and only a weak infrequent signal in tumor cells." (PMID 27362805, 2016). "The majority of non-tumor-infiltrating CD3+CD56+ NKT-like cells produced IFN-γ and TNF-α, but in tumors, we observed that significantly lower frequencies of IFN-γ and TNF-α-producing CD3+CD56+ NKT-like cells than those in non-tumor tissues." (PMID 27409423, 2016). "TNF-α has dual effects on tumours (anti-cancer or pro-cancer effect), which are due to the activation of different downstream signalling pathways followed by the combination of TNF-α and its receptor TNFR1." (PMID 27009073, 2016). "Th1 cells, a subset of CD4+ T cells, constitutively express IFN-γ and TNF-α, and play a role in priming tumor-specific CTLs through the release of soluble IL-2 in the proximity of CTLs." (PMID 26795730, 2016). "Altered expression of the genes coding for TNF-α and its receptors was observed in neoplastic diseases." (PMID 26896068, 2016). "In a recent study by our group using a mouse model of chemically induced colon carcinogenesis, we showed that tumor-bearing animals treated with jacalin produced increased levels of proinflammatory cytokines such as IL-1β, TNF, IL-12, and IFN-γ." (PMID 27119077, 2016). "As a pleiotropic cytokine, TNF-α has attracted attention because of its involvement in the promotion of inflammatory response, autoimmune, endocrine and neoplastic diseases." (PMID 26837816, 2016). "Several studies reported that the cytokine TNF-α is involved in tumor cell motility and invasion of various cancer including TNBC." (PMID 26888313, 2016).
tumor (continued). "Levels of IL-6, IL-1β, and tumour necrosis factor-α (TNF-α) in tumour tissue were 6.41−, 1.97−, and 1.83-fold higher in mice treated with HTiO2 NPs and US than in saline-treated control animals." (PMID 26996446, 2016). "Compared with the U27 model group, the expression levels of TGF-β1 protein and TNF-α protein expression exhibited statistically significant decreased in the mice tumor tissues in the CTX administration group and the ASMq administration group." (PMID 27881109, 2016). "Concordantly, both TUNEL staining and immunofluorescence staining for cleaved caspase-3 revealed that TNFα or IFNγ increased the number of apoptotic cells inside the tumor while conjugation with TCP-1 further induced apoptosis." (PMID 27342639, 2016). "By engaging the adaptive signaling programs of the TNF-R1 pathway, loss of PRL-3 expression induces cellular senescence and upregulates TNFα to convert senescent TNBC tumor cells into apoptotic cells." (PMID 27526109, 2016). "This phenomenon has been attributed to the secretion of TNFα from macrophages, because antibody neutralization of TNFα significantly suppressed macrophage-mediated tumor cell invasion." (PMID 27276704, 2016). "Among them, MCP-1 (CCL-2), IL-1b, IL-6, TNF-α were especially shown to be involved in the recruitment of immature cells into tumor microenvironment." (PMID 27993141, 2016). "TNF-α has been long been known to be at the center of immune disorders, inflammation, and tumor development, and subsequent research has revealed that it also functions as a pivotal regulator in energy metabolism." (PMID 27324794, 2016). "Although certain mechanisms governing cross talk between microenvironment and tumor cells have been previously elucidated, the role of pro-inflammatory cytokines, such as TNF, IL-6, and IL-1, is not completely understood." (PMID 27148266, 2016). "TNF-α and IL-6, reported as regulatory cytokines in the tumor microenvironment, have also been revealed as potential prognostic serum biomarkers in early-stage HCC35." (PMID 27117207, 2016). "Differences were also seen in the cytokine production profile from both tumor cells themselves or in serum exosomes of tumor‐bearing mice, with enhanced IL‐6 and IL‐17, and moderately decreased TNFα in 4THM versus EMT6 tumor bearers." (PMID 26725371, 2016). "The result suggested that BF-rTK + GCV administration (i.v) inhibits the expression of the major tumor inflammatory marker, TNF-α, in tumor microenvironment." (PMID 27464624, 2016). "Aqueous extract of Korean mistletoe (Viscum album coloratum) retards tumour metastasis via expression of TNFα." (PMID 27548121, 2016). "Significant tumor-infiltrating TNF-producing neutrophils along with a decrease in intratumoral IL-10 levels and a reduction of regulatory T cells (Tregs) in draining lymph nodes were observed in both models." (PMID 26973649, 2016). "The most well described cytokine involved in the expression of pro-proliferating integrins in cancer is tumor necrosis factor-α (TNF-α), which is a pro-inflammatory cytokine that is involved in tumor associated inflammation." (PMID 27929432, 2016). "Taken together, our data strongly suggests that one possible mechanism through which RCE inhibits invasion and tumor growth involves inhibition of IL-6, IL-8 and TNF-α pathways." (PMID 26888313, 2016). "Ascophyllan treatment led to marked increases in the percentage of IL-6-, IL-12- and TNF-α-producing DCs in spleen of tumor-bearing mice." (PMID 27008707, 2016). "To study the impact of systemic TNF ablation on the functional properties of MDSCs, we examined ROS and NO production in vivo by blood MDSCs of tumor-bearing hTNF KI mice undergoing treatment with TNF inhibitors." (PMID 27148266, 2016). "The expressions of TNF‐α, MMP9, HIF‐α, VEGF, NF‐κB, and IL‐1β were associated with the infiltration of inflammatory cells and the inhibition rate of tumor cells." (PMID 27734611, 2016).